ACOX1 (acyl-CoA oxidase 1)
Diseases named in the same sentence as ACOX1 in open-access papers (continued):
Sharing a sentence is not in itself a finding about the gene and the disease.
autosomal dominant polycystic kidney disease (1 paper, 2024). Autosomal dominant form of polycystic kidney disease. "Other studies also showed induction by FF of the protein or mRNA levels of Acox1, Mcad, and Cpt1 in young mice fed HFD or in a mouse model of autosomal dominant polycystic kidney disease." (PMID 38474282, 2024).
dementia (1 paper, 2024). Loss of intellectual abilities interfering with an individual's social and occupational functions. "Meanwhile, the reduced expression of the ACOX1 and VEGFA genes showed a prognostic value in the risk of MCI and dementia." (PMID 39125683, 2024). "In a comparative analysis of gene expression in MRI type 2, we found a decrease in the expression of ACOX1, BIN1, CD2AP, CD33, TNFR1, VEGFA, and VEGFC genes in clinically significant CI (MCI and dementia) compared to the control group." (PMID 39125683, 2024).
E. coli infection (1 paper, 2018). "Acox1 mRNA levels were similar in Mkp-1+/+ and Mkp-1−/− mice, and were decreased in both genotypes upon E. coli infection." (PMID 30563203, 2018). "We think that the liver likely synthesizes triglyceride for consumption by other organs, because both the mitochondrial fatty acid β-oxidation-related Cpt1a protein) and peroxisomal fatty acid β-oxidation protein Acox1 are downregulated in Mkp-1+/+ mice after E. coli infection." (PMID 30563203, 2018).
Encephalopathy (1 paper, 2021). Encephalopathy is a term that means brain disease, damage, or malfunction. "Bezafibrate, a pan-PPAR agonist, can significantly increase the levels of CD36, ACOX1, CPTI, CPT II, and uncoupling protein-2/3 (UCP-2/3), improve mitochondrial ΔΨm, restore intracellular ATP level, and further improve IAV-associated encephalopathy." (PMID 34540999, 2021).
esophageal adenocarcinoma (1 paper, 2022). A malignant tumor with glandular differentiation arising predominantly from Barrett mucosa in the lower third of the esophagus. "The higher expression levels of ACOX1 were related to poorer prognosis in esophageal squamous cell carcinoma (p = 0.0051), but better prognosis in esophageal adenocarcinoma (p = 0.01)." (PMID 36147494, 2022).
heart failure (1 paper, 2024). Inability of the heart to pump blood at an adequate rate to meet tissue metabolic requirements. "More obviously, ACOX1 catalyzes the initial and rate-limiting step in peroxisomal beta-oxidation of fatty acids, a process with emerging implications for heart failure." (PMID 39045004, 2024).
invasive breast carcinoma (1 paper, 2017). A carcinoma that infiltrates the breast parenchyma. "In a univariate analysis of all invasive breast cancers (n = 584), a shorter DFS was associated with HSL negativity (p = 0.024) and acyl-CoA oxidase 1 positivity (p = 0.028), whereas a shorter overall survival (OS) was associated only with acyl-CoA oxidase 1 positivity (p = 0.027)." (PMID 28124996, 2017).
lipodystrophy (1 paper, 2023). A congenital or acquired disorder characterized by abnormal loss or redistribution of the adipose tissue in the body. "ACOX1, ALDOB, protein kinase AMP-activated catalytic subunit alpha 2 (PRKAA2), JAK3, and protein tyrosine phosphatase non-receptor type 11 (PTPN11) have been confirmed to be closely related to β-oxidation of fatty acid, lipogenesis, cholesterol metabolism, and lipodystrophy." (PMID 36397714, 2023).
periodontitis (1 paper, 2025). An acute or chronic inflammatory process that affects the tissues that surround and support the teeth. "Furthermore, the downregulation of DBT, ACOX1, ACAA2, and HADHA in the liver provides valuable insights for developing therapeutic strategies for periodontitis-associated NAFLD." (PMID 40951429, 2025). "Based on these findings, DBT, ACOX1, ACAA2 and HADHA emerge as potential key targets linking periodontitis to NAFLD." (PMID 40951429, 2025).
protein deficiency (1 paper, 2021). "All infants that screen positive are referred to Gifu University, and ALD can be diagnosed within 5 days, and PD with increased VLCFA other than ALD, such as PBD, Acyl-CoA oxidase 1 deficiency, and D-bifunctional protein deficiency can be diagnosed promptly using our diagnostic system." (PMID 34449525, 2021).
Sepsis (1 paper, 2018). Sepsis is defined as life-threatening organ dysfunction caused by a dysregulated host response to infection. "ACOX1, one of the targets of LPS, has proven anti-inflammatory properties and, in the context of sepsis, its preservation by oils, under signaling adaptations abundantly developed above, might contribute to liver protection." (PMID 29765501, 2018). "On this light, it may be considered that the role of sepsis-mediated inhibition of ACOX1 might have been overlooked in the inflammatory challenge raised by sepsis in liver." (PMID 29765501, 2018). "In our previous study on mouse model for sepsis, LPS induced a deep drop in PGC-1α; argan oil effectively protected ACOX1 and removed energy metabolic reprogramming as attested by full restitution of PGC-1α." (PMID 29765501, 2018).
Zinc deficiency (1 paper, 2013). A deficiency of the essential metal Zinc; an essential cofactor for many enzymes. "As expected, zinc deficiency alone increased hepatic triglyceride, cholesterol and FFA levels in association with down-regulation of PPAR-α and lipid metabolism genes including Acsl1, Acox1 and Apob." (PMID 24155903, 2013).
tumor (35 papers, 2015 to 2026). "The mRNA and protein levels of ACOX1 were significantly downregulated in ccRCC, and its downregulation was closely associated with the tumor-node-metastasis stage of patients." (PMID 37724116, 2023). "Alterations in the lipidosome of OSCC caused by ACOX1 silencing enhance the motility and fitness of these tumor cells." (PMID 37371814, 2023). "Crucially, the HSP90AB1 K265R mutation or pharmacological inhibition of ACOX1 (10,12-tricosadiynoic acid) or TXN (1-methyl-propyl 2-imidazolyl disulfide, PX-12) synergizes with cisplatin to suppress tumor growth in vivo by disrupting redox adaptation." (PMID 41675575, 2026). "The protein level of ACOX1 was additionally higher in malignant tumor tissue of normal-weight women compared to normal-weight women with benign tumors." (PMID 38247846, 2024). "ACOX1, a key enzyme in fatty acid β-oxidation, acts as a tumor suppressor, and the downregulation of ACOX1 promotes CRC progression." (PMID 38844980, 2024). "The results showed that ANXA5, MMP1, MTR, REN, SCN4A, and SMAD3 were upregulated in HC samples, while HP and ACOX1 were downregulated in tumor tissues." (PMID 38599581, 2024). "Stimulated lipolysis in malignant CAAT supported upregulated peroxisomal and mitochondrial β-oxidation in both CAAT and tumor tissue since they generally displayed increased protein level of ACOX1 and ACADM." (PMID 38247846, 2024). "Exposure of cells to IFN-γ promotes the release of lys in CD8+ T cells, increases protein expression of SCL7A2, ACOX1, and Kcr, and inhibits cell viability and tumor growth." (PMID 39513918, 2024). "Consistent with the result above, ACOX1 overexpression by lentivirus inhibited tumor growth in PDX models." (PMID 36878899, 2023). "Together, these findings suggest that ACOX1-mediated ATIC acetylation is critical for tumor suppression." (PMID 36750554, 2023). "Meanwhile, ACOX1 overexpression also effectively inhibited ATIC activity in mouse xenograft tumor tissues." (PMID 36750554, 2023). "The results of our study have revealed that ACOX1 is a tumor suppressor and critical for the supervision of β-catenin signaling by regulating PA-mediated β-catenin palmitoylation and stabilization." (PMID 36878899, 2023). "Together, these results identify ACOX1 as a tumor suppressor, the downregulation of which increases PA-mediated β-catenin palmitoylation and stabilization and hyperactivates β-catenin signaling thus promoting CRC progression." (PMID 36878899, 2023). "Univariate and multivariate Cox regression analysis was carried out to assess the importance of ACOX1 expression for CRC prognosis together with other risk factors including age, TNM stage, or tumor differentiation." (PMID 36878899, 2023). "In contrast, mice treated with ACOX1 S26A exhibited similar tumor burdens and pathological features as the controls." (PMID 36878899, 2023). "Meanwhile, β-catenin target genes were upregulated in tumor tissues and metastasis samples with lower levels of ACOX1 in public databases." (PMID 36878899, 2023). "In parallel to a clear increase on MCT2 expression from non-tumour to localized tumour cells, we have also observed a rise in the expression of specific key proteins involved in peroxisomal β-oxidation: ACOX1 and ACOX3." (PMID 25639644, 2015). "The anti-tumor actions of ACOX1, ACAT1, ACADVL, and ACADM were identified as prospective targets." (PMID 37538114, 2023). "Based on the expanded correlation analysis results, we found that ACOX1, ALDH2, FUT6, and LRRC19 have a high association with GPX3 and DIO1 in the TCGA database, whether it is only tumor samples or “tumor samples + normal samples”." (PMID 32316597, 2020).
tumor (continued). "In 786-O primary tumor cell line we observed decrease expression of genes of insulin-associated proteins (IRS2, CBL), transcription regulators (AEBP1), PI3 kinase signaling (AKT1, BCL2L1) as well as lipid metabolism genes (ACOX1)." (PMID 30929166, 2019). "According to these findings increased ACOX1 succinylation might lead to excess H2O2 generation in the tumor cells thereby promoting the transformation of healthy into tumor cells." (PMID 30219925, 2018). "In addition, silencing of CD147 also down-regulated FASN and ACOX1 in tumor tissues (P < 0.01)." (PMID 37880644, 2023). "In addition, ACOX1 acts as a target gene of mir-15B-5p to inhibit tumor cell metastasis." (PMID 36878899, 2023). "Therefore, whether ACOX1-mediated PA reprogramming affects tumor progression by regulating protein palmitoylation remains unknown." (PMID 36878899, 2023). "This leads us to speculate that ACOX1 might act as a tumor suppressor in ccRCC as well." (PMID 37724116, 2023). "First, it indicates that more a tumor is acidotic (ie, more it contains acidic areas), more it will respond to PUFA supplementation and ACOX1 inhibition." (PMID 40726407, 2025). "In tumor samples taken from the GSE45001 and GSE32879 datasets, seven genes (APOA2, CAT, ACOX1, APOE4, AGXT, EHHADH, and HSD17B4) showed a substantial downregulation." (PMID 38274331, 2024). "Upregulation of SLC7A2 enhances ACOX1 expression and mediates CD8+ T cell histone Kcr to promote lysine release and inhibit tumor growth in TNBC patients." (PMID 39513918, 2024). "Overexpression of ACOX1 significantly antagonizes the depletion of SLC7A2 and inhibits tumor cell proliferation and growth." (PMID 39513918, 2024). "Knockdown experiments reinforced that diminished ACOX1 and CPT2 expression contribute to malignancy, influencing proliferation, apoptosis evasion, and tumor invasiveness." (PMID 38594466, 2024). "β-oxidation is mediated by acyl-CoA oxidases (ACOX 1–2) and the protein level of ACOX-1 was shown to be increased in HER2-cell line and tumor tissue compared with other BC subtypes." (PMID 32287294, 2020). "The expression of PLIN1 (p < 0.001), FABP4 (p = 0.029), CPT-1A (p = 0.001), ACOX-1 (p < 0.001), and FASN (p < 0.001) differed significantly among these tumor subtypes." (PMID 25751270, 2015). "Using patient‐derived tumor organoids and sera from human volunteers supplemented with polyunsaturated FA (PUFA), it is shown that inhibiting peroxisomal ACOX1 selectively kills acid‐exposed cancer cells, an effect exacerbated by pharmacological stimulation of glycolysis." (PMID 40726407, 2025). "Quantification of non‐necrotic cancer cells in tumor sections using a pan‐keratin antibody confirmed that ACOX1 inhibition significantly reduced tumor growth in mice fed the ω3 PUFA‐rich diet, but not in those on the control diet." (PMID 40726407, 2025). "However, in the GSE32879 dataset, only seven genes (APOA2, CAT, ACOX1, APOE4, AGXT, EHHADH, HSD17B4) were observed to be significantly reduced in tumor samples." (PMID 38274331, 2024). "Conversely, the expression of protective types (ACOX1, CPT2, ELOVL6, SUCLG2) was reduced in the H-R cohort than in the L-R cohort, implying that the eight-gene model accurately predicted prognosis and their possible effect on tumor incidence and growth." (PMID 38186579, 2023). "To define whether ACOX1 is a tumor suppressor in CRC, we ectopically expressed or silenced ACOX1 using Flag-tagged ACOX1 or ACOX1-specific short hairpin RNAs (shRNAs) in CRC cell lines (HCT15, RKO, HCT8, HCT116, and SW620), respectively." (PMID 36878899, 2023). "Similarly, the administration of 2% Pc-Ex mitigated the A549 tumour-induced upregulation of WAT metabolism-related gene (Pgc1a and Acox1) in epididymal WAT." (PMID 35406121, 2022).
tumor (continued). "In an evaluation according to ILC histologic type, CPT-1 and acyl-CoA oxidase 1 were more highly expressed in pleomorphic-type tumors (p = 0.029 and p = 0.014, respectively), whereas perilipin A expression was absent in tumor cells." (PMID 28124996, 2017). "When comparing expressions of lipid metabolism—related proteins among molecular subtypes, the expression of PLIN1 (p < 0.001), FABP4 (p = 0.029), CPT-1A (p = 0.001), ACOX-1 (p < 0.001), and FASN (p < 0.001) differed significantly among the different tumor subtypes." (PMID 25751270, 2015). "Our findings indicated that the tumor suppressor SDHC could repress fatty acid synthesis by decreasing the expression of ALDH3A2 and simultaneously promote FAO by upregulating the FAO-related enzymes ACOX1 and CPT1A through the PI3K/AKT signaling axes." (PMID 38844980, 2024). "Interestingly, the authors report that while ACOX1 protein levels were comparable or slightly reduced if compared to surrounding liver tissue, ACOX1 activity was elevated, and SIRT5 expression decreased in most of the tumor samples." (PMID 30219925, 2018). "Additionally, among downregulated hub genes, the expression of acyl-CoA oxidase 1 (ACOX1), apolipoprotein A2 (APOA2), apolipoprotein B (APOB), fibrinogen alpha chain (FGA), and fibrinogen gamma chain (FGG) were negatively correlated with the tumor stage of CCA patients." (PMID 35326644, 2022).
cancer (21 papers, 2016 to 2025). A tumor composed of atypical neoplastic, often pleomorphic cells that invade other tissues. "As performing the first step of peroxisomal β-oxidation, which is the major enzymatic step, an aberrant expression of ACOX1 has been implicated in a variety of cancers." (PMID 37724116, 2023). "Protein evidence of this reaction’s associated gene, ACOX1, supports this exclusion from cancer models, suggesting an alternate pathway for palmitoyl-CoA oxidation in cancer tissues." (PMID 26942765, 2016). "This prompted us to identify the inhibition of peroxysomal ACOX1 activity as a selective mode of acid‐exposed cancer cell killing." (PMID 40726407, 2025). "Accumulation of PA induced by enhanced ACOX1 dephosphorylation promotes palmitoylation of β-catenin, providing an additional layer of regulation to enhance β-catenin signaling in cancer." (PMID 36878899, 2023). "It has been demonstrated that the upregulation of ACOX1 in lymphoma promotes cancer cell proliferation, while its downregulation inhibits proliferation and induces apoptosis." (PMID 37724116, 2023). "Together, 183 proteins changed upon FGF19 treatment that were involved in different aspects of metabolism (e.g. Acot2, Acox1 and Acsl3) and 267 in cell survival/cancer (Col6a3." (PMID 28178326, 2017). "To explore in vivo the pro‐acidification strategy to sensitize cancer cells to PUFA, we fed mice either with control diet or isocaloric ω3 PUFA‐rich diet, and after two weeks of diet habituation, we injected SiHa cancer cells knockdown for ACOX1 (vs control SiHa cells)." (PMID 40726407, 2025). "Here, we showed that inhibiting the peroxisomal enzyme ACOX1 may actually overload the capacity of LD formation to act as a salvage pathway for acid‐exposed cancer cells." (PMID 40726407, 2025). "Our results reveal an unexpected role of PA reprogramming induced by dephosphorylation of ACOX1 in activating β-catenin signaling and promoting cancer progression, and propose the inhibition of the dephosphorylation of ACOX1 by DUSP14 or β-catenin palmitoylation as a viable option for CRC treatment." (PMID 36878899, 2023). "Notably, ACOX1 was reported to play important roles in cancer development of HCC by stimulating hepatic fatty acid oxidation and H2O2 accumulation." (PMID 32117713, 2020). "The signature genes, including CYR61, MMP28 and ACOX1, may play important roles in the initiation and progression of cancer." (PMID 30819200, 2019). "Acyl-CoA oxidase 1 (ACOX1) represses CRC growth through modulating palmitic acid in β-catenin activation and cancer progression." (PMID 38186579, 2023). "One key family of enzymes in this process are the peroxisomal acyl-CoA oxidases (ACOX1, ACOX2 and ACOX3), the expression of which has been shown to be dysregulated in some cancers." (PMID 35999530, 2022). "Of note, this study for the first time revealed that the dysregulation of MAPK1, ACOX1, SCP2, and NLN is significantly correlated to the survival time in EC patients, whose functional importance had been implied in multiple cancer types." (PMID 34124063, 2021). "Some of them have been reported as biomarkers in other types of cancers, such as GSTK1, IDH2, CAVIN3, HMGCS2, and ACOX1." (PMID 34557266, 2021). "As fatty acid oxidation (FAO) played an important role in lipid metabolism reprogramming in several types of cancer, we also analyzed the levels of critical FAO-related factors, including CPT1A and ACOX1." (PMID 28604762, 2017). "A similar pattern was seen in the protein level of lipolytic enzyme ATGL and β-oxidation enzymes, ACOX1 and ACADM, whose protein levels were higher in malignant tumor tissue of obese women compared to malignant tumor tissue of normal-weight women but also compared to their benign counterparts." (PMID 38247846, 2024). "GSEA revealed that ACOX1 negatively correlated with Wnt signaling, but not other cancer-related signaling pathways." (PMID 36878899, 2023).
cancer (continued). "Similarly, the reaction ACOAO7p, dependent on the gene ACOX1, was largely included in healthy tissues and not cancer tissues according to experimental data." (PMID 26942765, 2016).
infection (9 papers, 2017 to 2025). The state of being infected such as from the introduction of a foreign agent such as serum, vaccine, antigenic substance or organism. "Genes commonly down-regulated by HIF-1 high activity and P. aeruginosa PA14 infection included genes for lipid metabolism (like dhs-25, fat-5, fat-7, gpdh-1, acs-1, acdh-2, gba-4, lipl-5 and others) acox-1." (PMID 38517909, 2024). "(F) Immunoblotting of host glycolytic (PGK), TCA cycle (PDHA1), and fatty acid oxidation (HADHA, ACOX-1) proteins under Sirt1 and Sirt3 knockdown condition of S. Typhimurium-infected RAW 264.7 macrophages at 16 hr post-infection." (PMID 39693143, 2024). "As ACOX1 is the main enzyme involved in metabolizing DHA, these observations suggest that DHA might be required during infection." (PMID 28257516, 2017).